MDM2 (MDM2 proto-oncogene)
Diseases named in the same sentence as MDM2 in open-access papers (continued):
Sharing a sentence is not in itself a finding about the gene and the disease.
tumor (continued). "25-OCH3-PPD also plays an essential role in inhibiting tumor growth, cell invasion, and the MDM2 pathway in BC." (PMID 35684353, 2022). "MDM2 was highly expressed in both the tissues and tissue associated EVs analysed when compared to NAT and NAT EV (mean: NAT = 0.076 ± sd 0.0009, RL tumour = 2.809 ± sd 1.240, p = 0.0029; NAT EVs 0.13 ± sd 0.11, RL tumour EVs = 1.9 ± sd 0.98; p = 0.002)." (PMID 36043432, 2022). "The immunohistochemical studies showed expression of murine double minute 2 (MDM2) antigen in both primary and recurrent tumor cells." (PMID 36555969, 2022). "The aim of this study was to examine the possible association between CDKN2A, MDM2, E2F2 and LTF mRNA expression in the OSCC tumour and margin samples and influence on clinical variables in the Caucasian Polish population." (PMID 36551770, 2022). "The MDM2 gene has been shown to be aberrantly upregulated in human tumor cell lines through gene amplification, increased transcription, and enhanced translation." (PMID 36038536, 2022). "In this study, we tested a “best-in-class” small-molecule MDM2 inhibitor, Navtemadlin which induces tumor growth reduction in vitro and in xenograft models in a dose-dependent manner." (PMID 36922937, 2022). "Genetic and pharmacological inhibition of MDM2 reduced cell proliferation and impaired tumour growth in the xenograft model, thus confirming the finding of the CRISPR/Cas9 screening." (PMID 35692096, 2022). "In our study, the presence of MDM2 amplification varied within the primary tumor in patient GU-hgMNG-14, but it was stable in the recurrent tumor, thus reflecting the malignant progression of the tumor." (PMID 35701666, 2022). "In contrast, the growth of MDM2 WT tumour appeared to be more aggressive since a clear tumour edge was hard to be found." (PMID 35692096, 2022). "Though clinical trials have demonstrated that MDM2 inhibitors have anti-tumor activity and acceptable safety profiles, some limitations exist, including the development of resistance and dose-limiting toxicity." (PMID 35454137, 2022).
tumor (continued). "In our study, P4 xenograft tumors derived from patient Case702 had the same MDM2 amplification as the original tumor, and its growth can be inhibited by RG7112." (PMID 35928724, 2022). "The immunohistochemical studies showed expression of murine double minute 2 (MDM2) antigen in several cells, both primary and recurrent tumor cells." (PMID 36555969, 2022). "Amplification of Mdm2/4 appears to promote tumor cell survival, drug resistance, invasion, and metastasis via E3 ubiquitin-mediated proteasome degradation." (PMID 36290859, 2022). "HCT116 cells were injected in the flanks of nude mice to establish tumors and after two weeks of tumor engraftment, mice were treated with the MDM2 inhibitor milademetan, nelfinavir, or both drugs in combination." (PMID 36456590, 2022). "Previous investigations have demonstrated correlations between MDM2 overexpression, aggressive tumor behavior, and poor prognosis in numerous cancers." (PMID 35326742, 2022).
tumor (continued). "We also found that MX69 inhibited the MDM2/c-Myc regulatory axis in vivo resulting in significant inhibition of tumor growth and prolonged survival of MM xenografted mice." (PMID 35326742, 2022). "As expected, the tumour tissues revealed the presence of MDM2 DNA (visualized as pink/red dots) and the presence of the CEP12 control (blue dots), whereas the normal tissues showed only the signal corresponding to the CEP12 probe." (PMID 36043432, 2022). "Our subsequent analysis provided potential chemotherapy regimens for this type of tumor, including MDM2, MEK, and mTOR inhibitors." (PMID 36569894, 2022). "In such mice, Usp15 deficiency enhanced MDM2/NFATC2 pathway-dependent T-cell activation in vitro and a strong T-cell tumor infiltration in vivo with a major contribution of T-cell-mediated IFN-γ within the anti-tumor immune response." (PMID 35884430, 2022). "In normal thyroid cell lines, in which p90RSK is less active, the amount of MDM2 is reduced compared to tumor thyroid cells." (PMID 36612117, 2022). "To further corroborate the results from gene perturbation, we examined the anti‐tumour effect of pharmacological inhibition of MDM2 using a selective small molecular inhibitor, RG7388." (PMID 35692096, 2022).
tumor (continued). "The DDLPS patient with undetectable amplification of MDM2 in cell-free DNA had the smallest tumor size (14cm) compared to the two patients with detectable amplification (19cm and 25cm)." (PMID 34986184, 2022). "A high frequency of MDM2 gene amplifications leading to overexpression has been identified in a variety of tumor types, including breast carcinomas, glioblastomas, B cell lymphomas, and myeloid neoplasms." (PMID 35408841, 2022). "In particular, Mdm2 is a highly relevant target for human cancers, as Mdm2 is overexpressed in numerous human cancers and its overexpression facilitates tumor formation in transgenic mouse models." (PMID 36180910, 2022). "Inhibition of MDM2 phosphorylation leads to cell apoptosis and cell cycle arrest, thus repressing tumor cell proliferation." (PMID 35875060, 2022). "In conclusion, our study affords consequential new insights into the in vitro and in vivo tumor-suppressing effects of the novel MDM2 inhibitor APG-115, alone and in concert with SOC agents, in AML cells and animal models." (PMID 33941774, 2021). "The third method is tumor genomic biomarkers, such as MDM2/MDM4 amplifications and EGFR alterations." (PMID 34733781, 2021). "The most recurrent genetic alterations in cancer are CNAs targeting oncogenes such as MDM2 and TRPM728,30–32, and we identified these tumor-associated amplifications in cfDNA via ddPCR in 1/3 and 1/8 cases, respectively." (PMID 33441840, 2021). "Overexpression of MDM2 drives breast oncogenesis and blocks apoptosis of breast cancer cells, resulting in resistance of tumor cells to CDK4/6 inhibitors." (PMID 34123801, 2021). "In MCF-7 and HepG2 xenograft models, intraperitoneal administration of SP-141 at a 40 mg/kg dose for 5 days a week decreased MDM2 levels in tumors and inhibited tumor growth significantly after 42 and 20 days of treatment, respectively." (PMID 33924734, 2021).
tumor (continued). "Of the ten OMM cases for which tumor samples were available, MDM2 amplification was found in 3/10 tumors and was detected in the plasma of 1/3 of the corresponding dogs." (PMID 33441840, 2021).